Y_RNA (Y RNA )
Gene: Miscellaneous RNA gene on chromosome 9 (133,337,728 to 133,337,824, reverse strand). Ensembl gene ENSG00000201451.
Homologues: Orthologues: chimpanzee Y_RNA (98% identical), guinea pig Y_RNA (81% identical). Paralogues in human: RNY4 (85% identical), RNY4P6 (82% identical), RNY4P23 (79% identical), RNY4P3 (79% identical), RNY4P7 (79% identical), RNY4P9 (79% identical), Y_RNA (79% identical), RNY4P14 (78% identical), RNY4P34 (78% identical), Y_RNA (78% identical), RNY4P10 (77% identical), RNY4P13 (77% identical), and 87 more.